BDNF (brain derived neurotrophic factor)
Diseases named in the same sentence as BDNF in open-access papers (continued):
Sharing a sentence is not in itself a finding about the gene and the disease.
cancer (continued). "However, although BDNF/TrkB signaling has been shown to contribute to aggressive phenotypes in some cancers, no reports have investigated the biological significance of BDNF/TrkB signaling in GBC." (PMID 28423707, 2017). "However, no as-yet defined mechanism links the BDNF/TrkB pathway with cancer metastasis to a bone niche and subsequent osteolysis." (PMID 27458153, 2016). "All these genes (AP2M1, FKBP11, GALNT6, BDNF, COL9A3 and NR4A1) favor relevant features of cancer progression, indicating that their epigenetic activation in CTCs of CRC patients under treatment could be a key event for the development of therapy resistance and cancer progression." (PMID 38188020, 2023). "Hence, BDNF downregulation may be due to the presence of non-CNS malignant tumors, rather than chemotherapy treatment itself." (PMID 29179434, 2017). "However, the precise role of BDNF in the pathogenesis of cancer has not been fully explored." (PMID 23531103, 2013). "Cancer cells actively produce and secrete neurotrophic factors, notably nerve growth factor (NGF), brain-derived neurotrophic factor (BDNF), neurotrophin-3 (NT-3), and glial cell line-derived neurotrophic factor (GDNF)." (PMID 41009819, 2025). "IFGBP4, TPO, BDNF, and FGF-7 demonstrated higher FF levels in adolescents without cancer compared to donors." (PMID 39211054, 2024). "BDNF and FGF-7 levels were also significantly higher in FF of adolescents without cancer compared to the adolescents with cancer." (PMID 39211054, 2024). "This evidence indicates that BDNF/TRKB exhibits a direct role in the angiogenic process and can partially explain that the anti-angiogenic therapy with Bevacizumab (neutralizing antibody against VEGF) is not optimal in the cancer context." (PMID 31608227, 2019).
brain disorder (89 papers, 2009 to 2025). A disease affecting the brain or part of the brain. "In the embryonic and adult stages, an important contribution of BDNF/TrkB to neurogenesis is well recognized, and the changed neurogenesis is also associated with the pathophysiology of these brain diseases." (PMID 38338875, 2024). "BDNF has diverse roles in synapse function and plasticity and is implicated in the pathophysiology of various brain disorders." (PMID 36515276, 2022). "Despite the growing evidence for the involvement of BDNF and neuroinflammation in brain disorders, the association between the circulating level of BDNF and functional outcome after AIS is controversial." (PMID 36092813, 2022). "Brain derived neurotrophic factor (BDNF) level in different brain disorders and BDNF associated therapy." (PMID 36158555, 2022). "The single nucleotide polymorphism rs6265, also known as the Val66Met polymorphism, is one of the most characterized polymorphism in relation to BDNF function and risk of brain disease." (PMID 34071978, 2021). "Recently, many researchers have focused on possible relationship between BDNF polymorphism and brain disease including neuropsychiatric disorders." (PMID 30463271, 2018). "The BDNF Val66Met polymorphism, in which a valine is replaced with a methionine in the pro-peptide, is associated with brain diseases." (PMID 28498321, 2017). "Together, these findings suggest a new role for the BDNF pro-peptide, and provide insight into the common BDNF Val66Met polymorphism, which affects brain functions and is associated with brain diseases." (PMID 28498321, 2017). "PSD-95 itself and its interaction with BDNF signaling have been implicated in diverse brain diseases." (PMID 26448879, 2015). "By reducing psycho-endocrine stress load in the general populations, contemplative mental training may stimulate endogenous BDNF levels, thus promoting brain health and potentially counteracting risk factors for brain disorders." (PMID 39896238, 2025). "Interestingly, the BDNF Val66Met polymorphism, found in the pro-domain of the human BDNF protein, is associated with increased susceptibility to a variety of brain disorders." (PMID 37238659, 2023). "Our results suggest that 1,5-AF has preventive effects on aging-associated brain diseases via the AMPK/PGC-1α/BDNF pathway; these findings may encourage further clinical trials of 1,5-AF." (PMID 37950725, 2023). "Thus, we investigated the effects of 1,5-AF on the AMPK/PGC-1α/BDNF pathway in multiple animal models of human aging-associated brain diseases." (PMID 37950725, 2023). "Taken together, these computational evolutionary analyses provide important context as to the origins and sensitivity of genetic changes within BDNF that may help to deconvolute the role of BDNF polymorphisms in human brain disorders." (PMID 35732627, 2022). "Defective expression of BDNF has widely been associated with several brain disorders including HD." (PMID 31068790, 2019). "The current findings can explicate previously unknown aspects of the role of BDNF in the perturbed systems associated with brain diseases and neuropsychiatric disorders that exhibit altered BDNF signaling and reduced AMPAr levels." (PMID 23460828, 2013). "Finally, exercise may have beneficial effects on aging-associated brain diseases by activating the AMPK/PGC-1α/BDNF pathway, indicating that some compounds can mimic the central effects of exercise." (PMID 37950725, 2023). "Thus, our findings conform with these observations and call for future studies investigating potential interaction of Bassoon and BDNF/TrkB-mediated signalling in the pathogenesis of brain disorders that are associated with aberrant circuit maturation (e.g., synaptic pruning)." (PMID 34360710, 2021). "Taken together, how to enhance the BDNF/TrkB system is a promising target for therapeutic development in these brain diseases." (PMID 40005159, 2025).
brain disorder (continued). "Therapeutics that target BDNF/TrkB signaling are thus of interest as disease-modifying agents in several brain disorders." (PMID 38856179, 2024). "While these studies clearly indicate that BDNF plays a role in liver and brain diseases, further studies are warranted to elucidate its downstream effects in the CNS and periphery." (PMID 37377968, 2023). "In a study by Requena-Ocaña and colleagues, BDNF and neurotrophin-3 concentrations were related to the cognitive reserve and the individual’s ability to manage a brain disease through compensatory mechanisms of cognitive stimulation." (PMID 37509436, 2023). "BDNF is critical for brain development and plays an important role in stress responses and brain disorders." (PMID 37106749, 2023). "Considering the therapeutic implications, targeting BDNF signaling pathways holds promise as a potential strategy for the management of stress-related brain diseases." (PMID 37781095, 2023). "It is also unclear if the BDNF‐induced chromatin changes are related to specific brain disorders and if changes in chromatin features induced by BDNF differ from other stimulatory events." (PMID 35996956, 2022). "It is possible that an upregulation of BDNF and/or TrkB is a beneficial target to improve the behavior of brain disorders displaying impaired neurogenesis." (PMID 35887075, 2022). "Treatment of brain disorders is generally accompanied by an alteration – usually an increase – in BDNF levels." (PMID 32088835, 2020). "Consistent with findings reported in health and in different brain diseases, it is supposed that BDNF plays an import role in this process because the improvement in spatial learning induced by exercise is reduced after the TrkB-BDNF receptor is blocked." (PMID 33584215, 2020). "The evidence addressing the interaction between cytokines and neurotrophins in the brain is scarce, despite the fact that there is accumulating evidence showing involvement of neuroinflammation and brain-derived neurotrophic factor (BDNF) in brain disorders." (PMID 32235786, 2020). "7,8-dihydroxyflavone (7,8-DHF), a flavonoid that targets the tropomyosin-related kinase B (TrkB) receptor of brain-derived neurotrophic factor (BDNF), exerts positive effects in various brain disease models." (PMID 31174258, 2019). "This review will summarize our current knowledge of BDNF in the pathophysiology of the most common brain disorders." (PMID 30117106, 2019). "Although the role BDNF plays in brain disorders is better understood now than at the time of its discovery, many key aspects of its complex regulatory programs remain a mystery." (PMID 31455240, 2019). "Despite the increasing evidence for the involvement of BDNF and neuroinflammation in brain disorders, there is scarce evidence that addresses the interaction between the neurotrophin and neuroinflammation in psychiatric and neurodegenerative diseases." (PMID 30117106, 2019). "In this review, we discuss actions of BDNF and related signaling molecules on CNS neurons, and their contributions to the pathophysiology of brain diseases." (PMID 30463271, 2018). "BDNF has attracted increasing interest as potential biomarker to support the diagnosis or monitor the efficacy of therapies in brain disorders." (PMID 29568518, 2018). "An extensively studied therapeutic strategy for the treatment of several brain diseases has been the administration of brain-derived neurotrophic factor (BDNF)." (PMID 28134845, 2017). "Brain-Derived Neurotrophic Factor (BDNF) has attracted increasing interest as potential biomarker to support the diagnosis or monitor the efficacy of therapies in brain disorders." (PMID 26656852, 2015). "The present results provide a basis for further assessment of abnormalities of BDNF-dependent gene expression in striatal cells and its potential involvement in HD or clinically relevant human brain disorders." (PMID 19390590, 2009).
brain disorder (continued). "The present review shows recent advances in the molecular mechanisms underlying the BDNF/TrkB system in neuronal survival and plasticity, providing critical insights into the potential therapeutic impact of BDNF mimetics in the pathophysiology of brain diseases." (PMID 40005159, 2025). "7,8-DHF is a well-studied molecule in brain disorder models characterized by impaired cognition, and widely regarded as a tropomyosin receptor kinase B (TrkB) agonist with brain-derived neurotrophic factor (BDNF)-mimetic activity." (PMID 38856179, 2024). "Moreover, previous studies have confirmed that BDNF over-expressing engineered MSC (BDNF-eMSC) after irradiation can enhance their efficacy in facilitating recovery from brain diseases in rodent models." (PMID 38886817, 2024). "In addition to AD, emerging evidence suggests that dysregulation of the BDNF/TrkB system also plays a crucial role in the pathophysiology of Parkinson’s disease (PD), another stress-related brain disease." (PMID 37781095, 2023). "The review paper highlighted the BDNF signalling pathway dysfunction in various brain diseases." (PMID 37077958, 2023). "Therefore, downregulation of the BDNF/TrkB system is critical for pathophysiology of brain diseases such as MDD and AD." (PMID 37781095, 2023). "Since BDNF downregulation and neuroinflammation play a crucial role in the pathogenesis of many brain disorders, the question arises whether BDNF can affect inflammatory-related processes and reduce pro-inflammatory progress." (PMID 37047292, 2023). "Indeed, BDNF concentration changes in neural areas became an essential research element on brain disorders due to high BDNF concentration and expression in the amygdala, hippocampus, and brain cortex." (PMID 36946840, 2023). "So we suppose that the abnormal expression of BDNF/proBDNF level may be largely due to the inflammatory in anesthesia/surgery-induced brain disorders which remained further testified in our future study." (PMID 35370607, 2022). "NT-3 or NT4/5 are less discussed in the pathogenesis of brain disorders than NGF or BDNF." (PMID 34827728, 2021). "It is therefore probable that astrocyte Kir4.1 channels regulate both the excitability and synaptic plasticity of neurons by controlling extracellular levels of K+ ions, glutamate, and BDNF in tripartite synapses, and are consequently involved in the development of different brain diseases." (PMID 34638578, 2021). "According to these findings, a post-translational mechanism of BDNF, proteolytic cleavage of proBDNF could be new mechanisms for the development of brain diseases (Castrén and Kojima, 2017)." (PMID 32351365, 2020). "Because of the pivotal role of microglial neurotrophins (such as BDNF), an insight into the miRNA-mediated regulation of neurotrophic factors may provide promising biomarkers for various brain diseases." (PMID 32508597, 2020). "It is already described that ECs secrete BDNF that significantly stimulates neurite outgrowth and even BDNF-based therapies are considered an attractive possibility for the prevention/treatment of various brain diseases." (PMID 33076927, 2020). "The initial findings suggest that BDNF may be more than a biomarker for brain disorders; it may also become a possible target for the treatment of brain disorders." (PMID 30117106, 2019). "Evidence from preclinical studies and clinical trials suggests that treatment strategies aiming to increase brain BDNF levels could have a beneficial effect on many brain disorders." (PMID 30117106, 2019). "Although the underlying molecular mechanism is still unknown, this finding might be of great interest for future studies aimed at developing therapeutic strategies for brain disorders with higher prevalence in women, in which BDNF plays a key role." (PMID 31379496, 2019).
brain disorder (continued). "Better understanding of the interaction between BDNF and neuroinflammation could open new ways for therapy management and could facilitate the development of new therapeutic strategies for brain diseases." (PMID 30117106, 2019). "Both neuroinflammation and altered BDNF expression are common phenomena in many brain disorders." (PMID 30117106, 2019). "Therefore, activation of the BDNF/TrkB system is an attractive therapeutic target to treat these brain diseases." (PMID 30463271, 2018). "The overall physiological functions may be better correlated by a balance of both pro and mature BDNF, so measuring BDNF as a ratio of pro: mature forms might be a more accurate reflection of BDNF effect in relation to brain disorders." (PMID 29858545, 2018). "This study demonstrates that cyclotraxin-B might not only be a powerful tool to investigate the role of BDNF and TrkB in physiology and pathology, but also represents a lead compound for the development of new therapeutic strategies to treat brain disorders." (PMID 20333308, 2010). "Numerous studies suggest that targeting BDNF and its TrkB receptor could be a promising therapeutic strategy for the treatment of brain disorders." (PMID 20333308, 2010). "Hence, there is a connection between central and peripheral BDNF, and that serum BDNF may reflect brain disorders." (PMID 38006577, 2024). "Furthermore, BDNF can alleviate microglial activation in several brain disease models." (PMID 37759796, 2023). "Interaction and ratio between proinflammatory cytokines and BDNF are also taken into account, since better understanding of the interaction between proinflammatory cytokines and BDNF is needed and the proinflammatory cytokine/neurotrophin balance may play an important role in brain diseases." (PMID 34841285, 2021). "Thus, measurement of serum levels of BDNF may provide information on brain diseases and blood samples may be drawn from living subjects to monitor disease progression or treatment efficacy." (PMID 26539329, 2015). "Moreover, the loss of neurotrophic factors such as glial cell line-derived neurotrophic factor (GDNF) and brain-derived neurotrophic factor (BDNF) with CNTF may be involved in the pathogenesis of brain diseases." (PMID 25799580, 2015). "Understanding the complex role of neurotrophins in brain diseases and health requires an understanding of the BDNF/proBDNF balance which regulates neuronal apoptosis." (PMID 40430064, 2025). "ICS II has been found to mediate signaling pathways, including BDNF/TrkB/CREB and Wnt/β-catenin, thereby improving cognitive function in various brain disease models." (PMID 40351431, 2025). "In this review, we introduce current evidence regarding the relationship among neurotrophins (especially, BDNF, NGF, and their receptors) and the disrupted neuronal function and related brain diseases." (PMID 35887075, 2022). "Brain-derived neurotrophic factor (BDNF) and its neurotrophin receptor, TrkB, play important roles in neuronal plasticity and in the pathophysiology of various brain disorders." (PMID 33195276, 2020). "Brain-derived neurotrophic factor (BDNF) plays an important role in neuronal plasticity and in the pathophysiology of various brain disorders." (PMID 27007747, 2016). "We discuss how BDNF, NGF, IGF-1, and LIF could potentially be used for the treatment of brain diseases." (PMID 39598254, 2024). "Although BDNF elevation signifies neuroinflammatory processes in brain disorders, its significance in peripheral nerve disorders is not fully understood." (PMID 34539561, 2021). "The neurotrophin Brain-Derived Neurotrophic Factor (BDNF) is one of the most promising biomarkers for brain disorders however, a definitive clinical validation is still lacking." (PMID 26656852, 2015).